RN7SKP72 (RN7SK pseudogene 72)
Gene: Miscellaneous RNA gene on chromosome 18 (1,323,794 to 1,324,085, reverse strand). Ensembl gene ENSG00000199197.
Homologues: Orthologues: chimpanzee 7SK (99% identical). Paralogues in human: 7SK (81% identical), RN7SKP176 (80% identical), RN7SKP255 (79% identical), RN7SKP217 (79% identical), RN7SKP9 (79% identical), RN7SKP211 (78% identical), RN7SKP90 (78% identical), RN7SKP37 (78% identical), RN7SKP230 (77% identical), RN7SKP130 (77% identical), RN7SKP203 (77% identical), RN7SKP189 (77% identical), and 284 more.